ANGPT2 (angiopoietin 2)
Diseases named in the same sentence as ANGPT2 in open-access papers (continued):
Sharing a sentence is not in itself a finding about the gene and the disease.
acute kidney injury (16 papers, 2014 to 2026). Sudden and sustained deterioration of the kidney function characterized by decreased glomerular filtration rate, increased serum creatinine or oliguria. "Increased plasma angiopoietin-2 levels are associated with increased fluid overload, hepatic and coagulation dysfunction, acute kidney injury, mortality, and plasma cytokines in human septic shock." (PMID 35331262, 2022). "We have previously reported the associations between serum concentrations of angiopoietin-2 and the development of acute kidney injury and renal failure in the course of AP as well as the severity of AP." (PMID 28368336, 2017). "Angiopoietin-2 and osteoprotegerin were both independent risk factors for acute kidney injury." (PMID 29872039, 2018). "Intestinal injury was associated with acute kidney injury (AKI), acidosis (P < 0.001 for both), and angiopoietin 2, a maker of endothelial activation." (PMID 36069443, 2022). "Area under the receiver operating characteristic curves (AUROC) for day-1 plasma levels of angiopoietin-2 and thrombomodulin in predicting development of acute kidney injury." (PMID 36354140, 2022). "Main outcome measures included inflammatory and endothelial biomarkers (IL-6, IL-8, angiopoietin-2, syndecan-1), body fluid composition assessed by bioelectrical impedance, and clinical outcomes, including acute kidney injury (AKI), ICU length of stay (LOS), and ICU mortality." (PMID 41938900, 2026). "Angiopoietin-2 showed increased odds for the development of acute kidney injury (OR 1.095 [95% CI 1.032, 1.169]; P = 0.004) and was furthermore associated with delayed extubation, longer time in the ICU, and a higher chance of prolonged dependence on vasoactive medication." (PMID 37552379, 2023). "In a small single-center study, serum angiopoietin-2 has been shown to positively predict AKI diagnosed, according to KDIGO and renal failure diagnosed according to modified Marshall scoring system during first 72 h of AP." (PMID 31366007, 2019). "Novel putative mediators of acute kidney injury (AKI) include immune-cell derived tumour necrosis factor-like weak inducer of apoptosis (TWEAK), angiopoietin-2 (Ang-2) and protein pentraxin-3 (PTX3)." (PMID 26519056, 2015).
glioblastoma (15 papers, 2009 to 2024). The most malignant astrocytic tumor (WHO grade IV). "Several tip cell markers, including VEGFR2, endocan/ESM1, and angiopoietin 2, are generally upregulated in tumor vessels and were identified in our analysis of genes associated with vascular abnormality in glioblastoma." (PMID 29763414, 2018). "ANGPT2 acts as a destabilizer for tumor vasculature, generating vascular leakage and pericyte dropout from the glioblastoma vasculature." (PMID 38411438, 2024). "Similar roles of ANGPT2 in tumor immunosuppression have been reported for non-small cell lung cancer and glioblastoma." (PMID 37887354, 2023). "In particular, ANGPT1 has a role in the pathological vascularization of malignant astrocytomas and the balance between ANGPT1 and ANGPT2 has prognostic value in patients with primary glioblastoma multiforme." (PMID 21726470, 2011). "In glioblastoma, breast, and colorectal tumors, there was also an enrichment of alternative angiogenic factors, including biglycan, ANGPT2, HPSG2, KDR, COL4A1, COL4A2, VWA1, and TIMP1, which may likely compensate for VEGF blockade." (PMID 37887354, 2023). "In the course of this process, which is known as vascular cooption, glioblastoma cells disrupt the astrocyte-vasculature interaction and organize themselves into cuffs around microvessels accompanied by upregulation of angiopoietin-2 (ANG-2) in the coopted vessels." (PMID 33918764, 2021). "ANGPT2 activates angiogenesis through VEGFA, normalizes tumor blood vessels, and promotes the malignant transformation of glioblastoma." (PMID 36588901, 2022). "In addition to this, molecules typically expressed on endothelial tip cells such as VEGFR-2, Neuropilin-1, Angiopoietin-2 (Ang-2), Integrin-ß1 and others have been described to be present in glioma vessels in situ, implying that tip and stalk cell phenotypes co-exist in the glioblastoma vasculature." (PMID 23143192, 2012). "In addition, targeting simultaneously the angiogenic factor angiopoietin-2 (Ang-2) and translocator protein (TSPO), both of which are overexpressed in bevacizumab-treated glioblastomas, with a bispecific Ab in bevacizumab-treated rats resulted in prolonged survival." (PMID 33530460, 2021).
chronic kidney disease (14 papers, 2013 to 2025). Impairment of the renal function secondary to chronic kidney damage persisting for three or more months. "Of interest, raised ANGPT2 levels are associated with systemic markers of inflammation in patients with chronic kidney disease and are predictors of mortality." (PMID 27207083, 2016). "For example, increased aortic stiffness is known to be a powerful independent predictor of mortality in individuals with type 2 diabetes, and recent work has shown that plasma ANGPT2 is associated with arterial stiffness in patients with chronic kidney disease." (PMID 27207083, 2016). "The increased expression of angiopoietin-2 in the right kidney of malignant hypertension might be interesting and worthy of further study in view of previous reports on the association of circulating angiopoietin-2 with renal injury in chronic kidney disease." (PMID 27625610, 2016). "Antibody-mediated TIE2 activation by endogeneous angiopoietin-2 prevents vascular injury and ensuing tubular injury and tubulointerstitial fibrosis in experimental chronic kidney disease." (PMID 40952790, 2025). "As per AKI, a recent study proposed Angpt2 as an independent predictor of adverse renal outcome in chronic kidney disease in both the general and the diabetic population." (PMID 33067928, 2020). "A recent study reported preliminary evidence that ANGPT2 is an independent predictor of adverse renal outcome in chronic kidney disease in both the general and the diabetic population." (PMID 27207083, 2016). "Our previous report also found that high Angpt2 level was significantly associated with major adverse cardiac events (MACEs) in chronic kidney disease (CKD) not on dialysis." (PMID 27991547, 2016).
heart failure (14 papers, 2013 to 2026). Inability of the heart to pump blood at an adequate rate to meet tissue metabolic requirements. "ANGPT2 is a well-established marker of endothelial activation and vascular permeability, directly linked to vascular pathophysiology and heart failure progression." (PMID 40823165, 2025). "Prior studies have shown that high ANGPT2 levels are linked to poor outcomes, including increased risks of hospitalization and mortality in heart failure patients." (PMID 40823165, 2025). "The authors identified priority candidate proteins associated with heart failure, including B-Type natriuretic peptide, troponin T, angiopoietin-2, thrombospondin-2, latent growth transforming factor-β-binding protein-4, and follistatin-related protein-3." (PMID 34948066, 2021). "Previous studies have shown higher angiopoietin-2 concentrations in patients with decompensated heart failure and cardiogenic shock." (PMID 33976254, 2021). "ANGPT2 appears to be a potential therapeutic option in experimental heart failure." (PMID 32575548, 2020). "The ratio of circulating ANGPT2 to ANGPT1, has been shown to have prognostic value for the detection of kidney disease and heart failure." (PMID 39472324, 2024). "However, combining the biomarkers identified here (BMP10, ANGPT2, FGF23) yielded larger improvements than NTproBNP in this cohort with known heart failure status." (PMID 37798357, 2023).
Stroke (13 papers, 2014 to 2025). Sudden impairment of blood flow to a part of the brain due to occlusion or rupture of an artery to the brain. "The ANGPT-TIE signalling pathway is a key regulator of vascular stability and is dysregulated in diseases including stroke and diabetic retinopathy, in which elevated ANGPT-2 is associated with BBB leakiness and endothelial apoptosis." (PMID 38182581, 2024). "A multi-center case–control study on stroke patients further showed the association of variants in the promoter of Angpt2 with stroke." (PMID 37533068, 2023). "In conclusion, these results indicate that Angpt2 promotes repair and attenuates ischemic injury, and that the mechanism of this is closely associated with angiogenesis in the brain after stroke." (PMID 36358355, 2022). "A relationship between the A allele and higher circulating ANGPT2 levels was observed in stroke patients." (PMID 32526933, 2020). "In order to explore whether the protective function of Angpt2 in stroke is associated with angiogenesis, which is in reference to CD34 expression level, we first evaluated whether ischemic injury could induce CD34 expression in the injured brain regions." (PMID 36358355, 2022). "Numerous studies have demonstrated that ANGPT2 is implicated in BBB leakage and neuronal damage in conditions such as AD and stroke." (PMID 40988927, 2025). "In summary, we used the transient middle cerebral artery occlusion (MCAO) model of cerebral ischemic injury in mice combined with Angpt2 administration to investigate the function of Angpt2 in stroke." (PMID 36358355, 2022). "Our results showed that the administration of Angpt2 reduced the infarct volume and neuronal loss, the mechanism of which was associated with magnified CD34+ vascular length and area after stroke." (PMID 36358355, 2022). "To confirm whether Angpt2 administration could improve damage caused by ischemic injury, we first measured the blood flow before and during MCAO, analyzing brain sections through TTC and CV staining to assess the validity of the stroke model." (PMID 36358355, 2022). "It was reported that estradiol regulates expression of ANGPT-1, but not ANGPT-2, through estrogen receptor α (ERα) in an experimental stroke model." (PMID 32409702, 2020).
acute respiratory distress syndrome (12 papers, 2012 to 2025). Progressive and life-threatening pulmonary distress in the absence of an underlying pulmonary condition, usually following major trauma or surgery. "Interestingly, in patients with acute lung injury/acute respiratory distress syndrome, higher angiopoietin-2, as well as vWF levels, were associated with pulmonary permeability oedema." (PMID 38257821, 2024). "A four-endothelial biomarker panel, including elevated angiopoietin-2/angiopoietin-1 ratio, vascular cell-adhesion molecule, and von Willebrand factor, is useful in identifying acute respiratory distress syndrome." (PMID 35160072, 2022). "These contain the Von Willebrand Factor responsible for micro-clotting and angiopoietin-2 which increases vascular permeability and plays a key role in the Acute Respiratory Distress Syndrome." (PMID 34867791, 2021). "ANGPT2 serum levels might be a potential biomarker for evaluating prognosis in patients with acute respiratory distress syndrome." (PMID 41244106, 2025). "Angiopoietin-2 (Ang-2), a marker of endothelial dysfunction, may predict acute respiratory distress syndrome (ARDS) outcomes, but its role in RIARDS is unclear." (PMID 41360733, 2025). "Angiopoietin-2 has also been shown to predict AKI in other patient populations, e.g., after myocardial infarction, after cardiopulmonary bypass, with acute respiratory distress syndrome, or among patients of intensive care unit." (PMID 31940861, 2020).
colon carcinoma (12 papers, 2008 to 2025). "On the other hand, upregulation of ANGPT2 was associated with liver metastasis in colon cancer." (PMID 33515271, 2021). "A recent work consolidates the current results by proposing an increased risk of colon cancer liver metastasis caused by the ERK1/2-stimulated upregulation of ANGPT2 and CXCR4, thereby proving a mechanism for how ERK1/2 signaling may promote colon cancer cell invasion." (PMID 38247543, 2024). "Together, high ANGPT2 plus high VEGF‐A expression predicts a significantly (P = 0.02) lower probability of survival in patients with colon carcinoma." (PMID 34102002, 2021). "In colon carcinoma, ANGPT2 and VEGF‐A expression is significantly higher (P < 0.0001) in the tumor compared to the adjacent normal colon, whereas expression of ANGP1, PDGFA, and FGF2 is significantly lower (P < 0.0001)." (PMID 34102002, 2021). "Increasing Angiopoietin-2 and its receptor Tie-2 induces early induction of pro-inflammatory factors related to the development of colon cancer, and an increase in angiogenin was found to be correlated with tumor vascularization." (PMID 32984039, 2020). "ANGPT2, in these in silico results, was restricted to renal and colon tumour tissue in adults and lung in the embryo." (PMID 18394197, 2008). "In our study, we similarly observed significantly reduced expression of ANGPT2 in both right- and left-sided colon cancers, with FLT1 and PGF showing even lower expression in left-sided colon cancer." (PMID 41441010, 2025). "FLT1, a member of the VEGF receptor (VEGFR) family, along with ANGPT2 and PGF, plays a role in vascular development and contributes to colon cancer progression." (PMID 41441010, 2025). "In patients with colon carcinoma (n = 262), high ANGP2 and VEGF‐A expression, individually, predicts a somewhat worse probability of survival compared to low ANGPT2 or VEGF‐A expression, whereas high or low ANGPT1, PDGFA, and FGF2 expression has no impact." (PMID 34102002, 2021). "Coincidentally, the combination of ANGPT2 and VEGFA inhibition and PD-1 blockade was shown to improve tumor control, supporting the rationale for co-targeting angiogenesis and immune checkpoints for colon cancer therapy." (PMID 30042763, 2018). "In colon cancer, an immunohistochemical study showed that the expression level of ANGPT2 protein was not related to the degree of differentiation and lymph node metastasis but to the depth of intestinal wall invasion, blood metastasis, and poor clinical prognosis." (PMID 36172371, 2022). "Importantly, we confirmed the correlation between MYBL1 and ANGPT2 expression in a large cohort of clinical HCC samples and several published datasets in pancreatic cancer, esophageal carcinoma, stomach adenocarcinoma, and colon cancer." (PMID 35987690, 2022).
Obesity (11 papers, 2011 to 2024). Accumulation of substantial excess body fat. "The dual role of angiopoietin-2 in the pathological processes in the airway and adipose tissue has the potential to be considered an important factor in obesity-induced vascular remodeling." (PMID 38562155, 2024). "The question then arises: Can Angpt2–ITGα5β1 treatment be a therapeutic strategy to normalize fat distribution and treat obesity-induced metabolic disorders?" (PMID 32532986, 2020). "To examine if dietary fat overload and obesity affect Angpt2 expression, we fed mice with high-fat diet (HFD)." (PMID 32532986, 2020). "Meanwhile, increased angiopoietin-2 levels were also observed in individuals with overweight and obesity compared to lean control subjects, further indicating the potential involvement of angiopoietin-2 in obesity-induced vascular remodeling." (PMID 38562155, 2024). "Angiopoietin-2 may emerge as a significant contributor to the development of obesity-induced vascular remodeling, as angiopoietins play crucial roles in regulating vascular remodeling in endothelial cells." (PMID 38562155, 2024). "Higher expression of ANGPT2, HIF-1a, EGFL6, several MMP genes, and GDF15 was observed in individuals living with obesity (p ≤ 0.008)." (PMID 38024342, 2023). "When we investigated the list of 162 DMRs mapping to annotated loci in further detail we observed other genes with known and potential roles in obesity and related traits (such as PRKCZ, NDUFS2, GATA2, FOXP2, ANGPT2, NCOR2, CPT1B, PTPN6)." (PMID 25651499, 2015). "Higher expression of angiopoietin-2 (ANGPT2), HIF-1α, EGF like domain multiple 6 (EGFL6), several MMP genes, and growth/differentiation factor-15 (GDF15) was observed in individuals living with obesity (P ≤ 0.008)." (PMID 35958557, 2022). "Furthermore, our results also revealed several common upstream regulators associated with immune regulation and resistance to obesity (IL-4, IL-5, IL-33, CD15, HGF, ANGPT2, VEGFA, and neuropilin 1 [Nrp1]), supporting a critical role of intestinal homeostasis in systemic pathogenesis of obesity." (PMID 36880999, 2023). "Additionally, a direct correlation between BMI and gene expression was observed for AGER, ANGPT2, CD68, IFI30, NOTCH3 and SPP1, whereas an inverse correlation was achieved for DLL4, PLIN, PNPLA2 and VEGF (genes that were down-regulated due to obesity)." (PMID 33022994, 2020).
atherosclerosis (10 papers, 2016 to 2023). A disease characterized by the build-up of fatty material and calcium deposition in the arterial wall resulting in partial or complete occlusion of the arterial lumen. "Dysregulation of Angpt1 and Angpt2 expressions by Rgp are also linked to progression of atherosclerosis." (PMID 36250046, 2022). "Angiogenesis and inflammation are implicated in aortic aneurysm and atherosclerosis and regulated by angiopoietin-2 (Angpt2)." (PMID 27767064, 2016). "More work is needed to determine the feasibility of long‐term administration of Angpt2 inhibitors for atherosclerosis." (PMID 36740996, 2023). "Angiopoietin-2 (Ang-2) is an important proangiogenic factor that also plays an important role in atherosclerosis." (PMID 30702576, 2019). "The effect of Angpt2 administration on experimental aortic aneurysm and atherosclerosis was examined." (PMID 27767064, 2016). "Rgp increases the expression of Angpt2 while decreasing the expression of Angpt1 in human aortic smooth muscle cells, inducing their migration, a crucial event in the pathophysiology of atherosclerosis." (PMID 36250046, 2022). "Angiopoietin-2 (Ang-2) is a proangiogenic factor that mediates inflammation and atherosclerosis." (PMID 32182213, 2020). "Up-regulation of Angpt2 may have potential therapeutic value in patients with aortic aneurysm and atherosclerosis." (PMID 27767064, 2016). "Given the significance of angiogenesis and inflammation in AAA and atherosclerosis, we hypothesised that Angpt2 would be important in the development of AAA and atherosclerosis and examined this in the angiotensin II (AngII)-infused Apolipoprotein E deficient (ApoE−/−) mouse model." (PMID 27767064, 2016). "As expected, we observed that laminar shear stress induces cell shape change, up‐regulates vasoprotective genes (such as CPY1B1, THBD and NOS3) and, however, down‐regulates pro‐atherosclerosis genes (such as VCAM1, CD36, and ANGPT2)." (PMID 34085389, 2021). "Here we provide in vivo evidence supporting a protective role for Angpt2 in experimental AAA and atherosclerosis." (PMID 27767064, 2016). "This study investigated the effect of Angpt2 on AAA development and atherosclerosis in the ApoE−/− mouse model." (PMID 27767064, 2016). "Secondly, since Angpt2 has many actions the precise mechanism by which rAngpt2 limited AAA and atherosclerosis in our study is not certain." (PMID 27767064, 2016). "The effect of Angpt2 on AAA and atherosclerosis has not previously been investigated in the AngII-infused AAA mouse model." (PMID 27767064, 2016).
Hypertension (10 papers, 2018 to 2025). The presence of chronic increased pressure in the systemic arterial system. "Circulating angiopoietin-2 levels are elevated in individuals with systemic hypertension and angiopoietin-1/angiopoietin-2 ratios are reduced in pregnant women who develop preeclampsia." (PMID 30234375, 2018). "For instance, high levels of an angiogenesis gene signature score at baseline, low baseline serum angiopoietin-2, or early induction of hypertension during treatment could identify responders and could help in a better selection of patients for future anti-VEGFR therapies." (PMID 39435288, 2024).